BECN1 (beclin 1)
Diseases named in the same sentence as BECN1 in open-access papers (continued):
Sharing a sentence is not in itself a finding about the gene and the disease.
leukemia (continued). "Our results suggest that infection of leukemia cells with an oncolytic adenovirus overexpressing Beclin-1 can induce significant autophagic cell death and provide a new strategy for the elimination of leukemic cells via a unique mechanism of action distinct from apoptosis." (PMID 23765161, 2013). "Together, these results suggest that CRAds armed with therapeutic transgenes such as Beclin-1 could eradicate leukemia stem cells although the exact effects of SG511-BECN on CD34+ leukemic stem cells has not been determined." (PMID 23765161, 2013). "Here, we investigated whether a strategy that combines the oncolytic effects of an adenoviral vector with simultaneous expression of Beclin-1, an autophagy gene, offers a therapeutic advantage for leukemia." (PMID 23765161, 2013). "This study suggests that As4O6 should induce Beclin-1-induced autophagic cell death as well as caspase-dependent apoptosis and that it might be a promising agent for the treatment of leukemia." (PMID 21912568, 2012). "This study provides evidence that As4O6-induced cell death is related to Beclin-1-induced autophagy as well as caspase-dependent apoptosis and As4O6 might be an effective agent for the treatment of leukemia similar to As2O3." (PMID 21912568, 2012). "Thus, CRAd with Ad5/11 fibers, expressing the Beclin-1 gene may offer a novel promising gene-virotherapy for the treatment of leukemia via a unique mechanism of action distinct from apoptosis." (PMID 23765161, 2013). "The interaction between Beclin-1 and the BCR-ABL oncogene in CML unveils another layer of complexity in autophagy’s role in leukemia." (PMID 38887520, 2024). "In leukemia THP-1 cells, β-elemene promotes dissociation of Bcl-2/Beclin-1 complex, leading to autophagosome generation and cell autophagy." (PMID 38879549, 2024). "The proteins mainly play a role in the two processes of autophagy initiation and mature autophagosome formation in leukemia, mainly ULK1 complex, Beclin-1 protein, and ATG-related proteins." (PMID 38887520, 2024). "The expression of proteins related to apoptosis and autophagy, including cleaved-PARP-1, Bcl-2, Bax, LC3-I/II, Beclin-1, Atg5, p62, phospho-AMPK, AMPK, phospho-mTOR, mTOR, phospho-Akt, and Akt, in human leukemia cells were evaluated using Western blotting." (PMID 36826047, 2023). "For example, miR-17-5p, the expression of which is increased in leukemia, promotes AML proliferation by inhibiting autophagy by targeting BECN1." (PMID 35526025, 2022). "miRNAs have a wide range of roles in leukemia, among which, miR-145 enhances the sensitivity of ALL cell lines to glucocorticoids, which is achieved by promoting the expression of Beclin-1 and Bax genes and inhibiting the expression of Bcl-2 genes to induce autophagy and apoptosis production." (PMID 38887520, 2024). "The studies show that overexpression of Beclin-1 significantly enhanced the killing effect of the virus on leukemia cell lines and primary leukemic cells, in which cytotoxic activity of the parental virus without Beclin-1 gene was weak overall." (PMID 23765161, 2013). "Further investigation into Beclin-1’s specific mechanisms of action and its interactions with oncogenes like BCR-ABL could unlock new avenues for treatment strategies aimed at leveraging autophagy modulation to combat drug resistance in leukemia." (PMID 38887520, 2024). "Chemical inhibition of autophagy, transfection of siRNA BECN1, or AMPK inhibition using compound C restored apoptosis in leukemia stem cells treated with JQ1 suggesting that, in these cells, autophagy acted as a pro-survival process which could be counteracted by a combined treatment." (PMID 31861179, 2019). "To further examine whether Beclin 1 regulates DNA DSB repair in an autophagy-dependent manner, we examined the effect of Beclin 1 on DNA DSB repair in cells that lack ATG7-dependent autophagy using Atg7-knockout K562 leukemia cells." (PMID 28345663, 2017).
leukemia (continued). "When the HL-60 leukemia cells were administrated with 5 μM, 10 μM and 15 μM of XN for 48 h, respectively, the increased expression levels of LC3-II and p62 but not Beclin-1 were found." (PMID 28415750, 2017).
viral infection (38 papers, 2013 to 2025). "Recent literature suggested that environmental factors such as nutritional deficiency and virus infection can stimulate Beclin-1 expression, but Beclin-1 expression induces autophagy and causes cell death." (PMID 35401922, 2022). "A deficiency in Beclin-1 reduces viral infection in mice and abolishes AaVA-1-mediated enhancement of ZIKV transmission by mosquitoes." (PMID 31937766, 2020). "For the instance of West Nile virus, stimulation of autophagy via apro-autophagic peptide (Tat-beclin 1-derived from a region of the autophagy protein beclin 1) can protect neuronal cells from cell death caused by the virus infection." (PMID 28119857, 2016). "It is pathologically triggered by prolonged starvation, hypoxia-ischemia, or viral infections, and experimentally induced by elevated concentrations of the autophagy-inducing peptide Tat-Beclin 1 in both cellular systems and in vivo models." (PMID 41471037, 2025). "Previous study has showed that NIb can be recognized by the autophagy protein Beclin 1 and degraded through autophagosomes inhibiting viral infection." (PMID 36715229, 2023). "In contrast, both levels of the vacuolar protein sorting 34 (VPS34) and Beclin-1, the downstream molecules which play essential roles in promoting the formation of autophagic vesicles, increased upon virus infection." (PMID 37114059, 2023). "In most examples discussed in the sessions above, Tat-BECN1 exhibits beneficial effects to cells or organisms under stress conditions, like protections against bacterial and viral infections, recoveries from injuries, detoxication of aberrant metabolism." (PMID 36172279, 2022). "Tat-BECN1 protects against viral infections, by inhibiting HIV replication in human monocyte-derived macrophages (MDMs) and memory CD4+ T cells, and by inhibiting Middle East respiratory syndrome coronavirus (MERS-CoV) replication in VeroB4 cells." (PMID 36172279, 2022). "For instance, RNF216 or SKP2 promotes K48-ubiquitination and destabilization of Beclin 1 to inhibit autophagy in response to pathogen or viral infection." (PMID 36528652, 2022). "During viral infections, Beclin-1, an autophagy protein required for nucleating autophagosomes, becomes activated when suppressive Beclin-1:Bcl-2 interactions are lost." (PMID 35681452, 2022). "The first example of virophagy has been observed during Sindbis virus (SINV) infection, in which Beclin-1 and Atg5 protect against viral infection and finally against SINV-mediated encephalitis." (PMID 34745965, 2021). "The inhibition of autophagy induction has been noticed for a broad range of viral infections mainly by targeting Beclin-1." (PMID 34745965, 2021). "Defects in the molecular machinery for macroautophagy, such as the genetic inhibition of ATG5 or beclin-1 (BECN1) genes, consequently make mice and primary human astrocytes more susceptible to viral infections." (PMID 33920748, 2021). "Autophagy is an essential cellular process affecting virus infections and other diseases and Beclin1 (BECN1) is one of its key regulators." (PMID 31852899, 2019). "A cell‐permeable, autophagy‐inducing Tat‐Beclin‐1 peptide, TB‐peptide, were previously demonstrated therapeutic benefits in disease models related to reducing viral infection, improving cardiac performance during pressure overload, and enhancing the effectiveness of chemotherapy." (PMID 33733054, 2021). "Additionally we found that Beclin-1 knockdown remained evident, albeit incomplete, at 24 h after viral infection (i.e. 72 h after siRNA transfection)." (PMID 25541728, 2014). "Although beclin-1 up-regulation is a frequent finding following viral infection, there are data of beclin-1-independent autophagy induction by enterovirus 71 and it has been reported a late and rather limited increase in the expression of this proautophagic protein by HSV-1." (PMID 24490870, 2014).
viral infection (continued). "Consistent with a protective role of autophagy in neurons, over-expression of Beclin 1 significantly improves motor symptoms in a mouse model of Machado-Joseph disease or spinocerebellar ataxia type 344, and expression of Atg5 protects neurons against virus infection-induced cell death." (PMID 26987296, 2016). "Knockdown of AMPK and genes encoding members of the phosphoinositide 3-kinase (PI3K) complex composed of the autophagy-related protein 14 (ATG14), BECN1, and vacuolar protein sorting 34 (VPS34) facilitated viral infection in leafhoppers." (PMID 40300033, 2025). "WIPI1 and Beclin-1 expression increased after induction of autophagy by torin, but little change in expression was detected in SK-N-SH or IMR-32 cells following virus infection for 3 h at a high MOI." (PMID 40042894, 2025). "Virus infection increased the protein levels of the autophagy markers ATG16L1 and Beclin-1 and the autophagy regulator mTOR." (PMID 23924832, 2013). "The high expression of BECN1 in hepatitis and HCC tissues may be promoted by viral infection-induced interferon-γ." (PMID 23833647, 2013). "However, silencing Rubicon, a participant in Beclin-1- mediated LAP, did not impair ZIKV load and even slightly enhanced the viral infection in the AaVA-1 incubated cells." (PMID 31937766, 2020).
neuroblastoma (36 papers, 2012 to 2025). Neuroblastoma (NB) is the most common solid, extracranial childhood tumor. "A study conducted on neuroblastoma cells revealed that overexpression of ATG5 or beclin-1 reduced angiogenesis, while silencing of ATG5 and Beclin-1 had the opposite effect." (PMID 38576024, 2024). "Specifically, depletion of Bcln1 by RNA interference in rat neuroblastoma cells expressing human AβPP transgene (B103/hAPPwt cells) increased AβPP, Lc3, and Aβ, while Becn1 overexpression reduced AβPP levels." (PMID 37718819, 2023). "Tat-BECN1 attenuates apoptosis and necrosis, in brain endothelial cells and renal epithelial cells exposed to high salt, in human neuroblastoma cells infected with WNV." (PMID 36172279, 2022). "CaMKII can phosphorylate Beclin 1 directly at Ser90, thereby promoting the ubiquitination of Beclin 1 and activating autophagy in neuroblastoma cells." (PMID 33714957, 2021). "It has previously been stated that the natural compound 18α-glycyrrhetinic acid and OxyR-mediated autophagy display accumulation of Atg5, Atg7, and Beclin-1 in neuroblastoma cells." (PMID 33800526, 2021). "HMGB1 overexpression also contributed to the chemoresistance of neuroblastoma cells by inducing Beclin-1-mediated autophagy." (PMID 28938696, 2017). "Beclin 1 was found to be highly expressed in neuroblastoma, and a combination of HCQ and vincristine significantly decreased its progression." (PMID 28938696, 2017). "We found that ionomycin/EB1089 can activate CaMKII to phosphorylate Beclin 1/Id-1, which further induces the differentiation of neuroblastoma cells." (PMID 29079782, 2017). "In four different neuroblastoma cell lines, CaMKII was effectively activated and the phosphorylation of Beclin 1 at Ser90 was also significantly increased." (PMID 29079782, 2017). "The pro-survival BCL2 proteins BCLXL as well as MCL1 which are both bound by NOXA in neuroblastoma cells inhibit autophagy by sequestration of BECN1." (PMID 28415610, 2017). "As BECN1 knockdown and 3MA efficiently reduced cell death, in neuroblastoma cells a sequential process of autophagy followed by death induction can be proposed." (PMID 28415610, 2017). "Similarly to our observations, the activation of autophagy by Rap in human SH-SY5Y neuroblastoma cells upregulates the expression of BECN1 and HIF-1α and enhances the protective effect against brain injury." (PMID 39943135, 2025). "Autophagy triggered by this re-assortment further causes degradation of Survivin, a recently identified key-player of autophagy in neuroblastoma, which further releases BECN1 from Survivin/BECN1 complexes and leads to a feed-forward enhancement of autophagic signaling." (PMID 28415610, 2017). "In MC65 human neuroblastoma cells, 100 μM phytic acid in the presence of tetracycline resulted in reduced concentrations of hydrogen peroxide and increased concentrations of proteins responsible for autophagy and housekeeping of the neuroblastoma cells (beclin-1 and SIRT1)." (PMID 34356337, 2021). "While ABT-199 successfully induces apoptosis in high BCL2-expressing neuroblastoma SHSY-5Y cells, BAU-243 triggered autophagic cell death rather than apoptosis in GBM A172 cells, indicated by the upregulation of BECN1, ATG5, and MAP1LC3B expression." (PMID 36309485, 2022). "Human neuroblastoma SH-SY5Y cells were exposed for 24 h to 10 μg/ml cinnamon extract (CCHE), and mRNA levels of three macroautophagy (LC3, beclin-1, and p62) and two CMA (Lamp2A and Hsc70) effectors were measured by real-time PCR." (PMID 35755250, 2022). "Transgenic expression of MCL1, however, indirectly slows down BECN1 activation by sequestering NOXA away from BCLXL, as NOXA binds MCL1 with higher affinity than BCLXL in neuroblastoma cells." (PMID 28415610, 2017). "Ours results also agree with recent findings, which have shown that ethanol up-regulates the expression of LC3-II and beclin-1 and the degradation of p62 in the developing brain and in SH-SY5Y neuroblastoma cells." (PMID 27070930, 2016).
neuroblastoma (continued). "Our results showed that human malignant neuroblastoma cells transfected with LC3 shRNA plasmid and concurrently treated with GST dramatically decreased expression of Beclin 1, further demonstrating the inhibition of autophagy." (PMID 24205354, 2013). "This supports the hypothesis that early during MG-2477-treatment BECN1 is displaced from BCLXL by increased amounts of cellular NOXA, which triggers autophagy initiation in neuroblastoma cells." (PMID 28415610, 2017).
liver fibrosis (31 papers, 2014 to 2025). "A recent study involving 74 individuals determined that serum Beclin-1 levels were associated with severe liver fibrosis." (PMID 40430125, 2025). "In a preclinical study of a mouse model of liver fibrosis induced by CCl4, exosomes containing miR–181–5p were shown to increase autophagy and decrease liver fibrosis caused by TGF-β1 by blocking the STAT3/Bcl-2/Beclin 1 pathway in HSCs." (PMID 41244150, 2025). "For example, YTHDF1 activates autophagy by stabilizing BECN1, leading to hepatic stellate cell ferroptosis and ameliorating liver fibrosis in murine models." (PMID 39897540, 2025). "Beclin‐1 is encoded by BECN1, which is the target gene of miR‐30a in cancer, hepatic fibrosis, or diabetic cataracts." (PMID 40318053, 2025). "Autophagy holds a significant role in the context of liver fibrosis, regulated by the activation of autophagy-related proteins, including Beclin-1 and LC3B." (PMID 38797855, 2024). "For example, HuR promotes the production of BECN1/Beclin1 by binding to AREs of BECN1 mRNA, activates the degradation of autophagy ferritin, and finally leads to iron-dependent siderosis in liver fibrosis." (PMID 39039254, 2024). "Western blot also showed that YC-1 significantly decreased the expression of PCSK9, LC3B-II, and BECN1, respectively, and increased the expression of p62 during liver fibrosis." (PMID 37466835, 2023). "BECN1 knockdown also attenuated inhibition of collagen deposition of MSC-ex on CCl4-induced liver fibrosis." (PMID 35395830, 2022). "In this process, upregulated ELAVL1 binds to BECN1 mRNA and promotes BECN1/Beclin1 generation, resulting in autophagy-dependent degradation of ferritin, HSCs ferroptosis, and attenuated liver fibrosis." (PMID 36703745, 2022). "In vivo, the ability of MSC-ex to induce ferroptosis and ameliorate liver fibrosis was weakened following BECN1 knockdown." (PMID 35395830, 2022). "Exosomal miR‐30a inhibits autophagy by targeting the Beclin‐1 signalling pathway and plays an important role in myocardial infarction (MI) and liver fibrosis." (PMID 33506641, 2021). "The results showed that mRNA levels of autophagy-related genes LC-3II and Beclin-1 in liver fibrosis model groups were significantly increased, while those in bergenin treatment groups were decreased in a dose-dependent manner." (PMID 33488687, 2020). "In these hepatic fibrosis models, increased expression of Beclin-1 and LC3 and a decreased expression of P62 are consistent with HSC activation by autophagy." (PMID 28839277, 2017). "We have demonstrated that exosomes containing miR‐181‐5p can increase autophagy and reduce TGF‐β1‐induced liver fibrosis by inhibiting the STAT3/Bcl‐2/Beclin 1 pathway in HST cells and a CCl4‐induced liver fibrosis mouse model." (PMID 28382720, 2017). "For example, recent study demonstrated that hUCMSC-Exo cargo BECN1 could induce HSC ferroptosis to achieve hepatic fibrosis mitigation." (PMID 36195966, 2022). "This study found MSC-ex-derived BECN1 induced HSCs ferroptosis and ameliorated liver fibrosis." (PMID 35395830, 2022). "MSC-ex may promote xCT/GPX4 mediated HSCs ferroptosis through the delivery of BECN1 and highlights BECN1 as a potential biofactor for alleviating liver fibrosis." (PMID 35395830, 2022). "The overexpression of miR‐30a may alleviate liver fibrosis by inhibiting autophagy mediated by the Beclin‐1 signalling pathway." (PMID 33506641, 2021). "The current study provides compelling evidence that the combined administration of PFD and LIR enhances the regenerative response, normalizes Beclin-1 expression, and modulates the NLRP3 inflammasome pathway, thereby alleviating liver fibrosis (LF)." (PMID 41413484, 2025). "Qu et al73 found that exosomes containing miR‐181‐5p increased autophagy and alleviated TGF‐β 1‐induced liver fibrosis by inhibiting the STAT3/Bcl‐2/Beclin‐1 pathway in HST cells and CCl4‐induced liver fibrosis in mice." (PMID 33506641, 2021).
liver fibrosis (continued). "Beclin-1 and LC3-II are markers of autophagy that are increased significantly during liver fibrosis, and bergenin effectively reduced their levels in the present work." (PMID 33488687, 2020). "With autophagy assessed in response to liver fibrosis by measuring the expression of LC3B, SQSTM1/p62, and BECN1, the conversion of LC3B-I to LC3B-II was an essential step in the formation of autophagosomes, and the abundance of LC3B-II correlated with the number of autophagosomes." (PMID 37466835, 2023). "In addition, MSC-ex-derived BECN1 decreased xCT/GPX4 expression and inhibited HSCs activation, providing a novel insight into the proferroptosis effect of MSC-ex in liver fibrosis." (PMID 35395830, 2022). "Moreover, Beclin-1 mRNA has been shown as a target of ELAVL1 to trigger autophagy and ferroptosis in liver fibrosis." (PMID 33568052, 2021). "After overexpression of BECN1 in human mesenchymal stem cells and extraction of the corresponding exosomes, this BECN1-enriched-exo could inhibit xCT-driven GPX4 expression thereby inducing ferroptosis to ameliorate liver fibrosis." (PMID 37733667, 2023).